SFTA1P (surfactant associated 1, lncRNA)
Synonyms: SFTPF
Gene: Long non-coding RNA gene on chromosome 10 (10,784,436 to 10,798,639, reverse strand). Ensembl gene ENSG00000225383.
Diseases named in the same sentence as SFTA1P in open-access papers:
SFTA1P is named in the same sentence as 19 diseases in open-access papers, as found by Europe PMC text mining. Sharing a sentence is not in itself a finding about the gene and the disease. The quoted sentences say what the papers report.
gastric cancer (3 papers, 2019 to 2022). A primary or metastatic malignant neoplasm involving the stomach. "Previous studies have showed that whilst LncRNA SFTA1P is up-regulated in hepatocellular carcinomas it is down-regulated in lung carcinoma and gastric cancer." (PMID 36344495, 2022). "Another DElncRNA, SFTA1P has been reported to be a tumor suppressor by inhibiting cell proliferation, invasion and migration in gastric cancer." (PMID 30755833, 2019).
liver cancer (2 papers, 2022 to 2023). An epithelial or non-epithelial malignant neoplasm that arises from the liver. "The lncRNA SFTA1P acts as an oncogene and promotes the growth and invasion of lung and liver cancers in various signaling pathways, such as mTOR signaling pathway, AKT signaling pathway." (PMID 36819091, 2023). "In the regulatory network constructed in the present study, lncRNA SFTA1P has been reported to downregulate miR-4766-5p through the PI3K/AKT/mTOR signaling pathway to promote liver cancer growth." (PMID 35155682, 2022).
lung adenocarcinoma (2 papers, 2017). A carcinoma that arises from the lung and is characterized by the presence of malignant glandular epithelial cells. "Based on the results derived from GEPIA, down-regulation of SFTA1P was found in the lung adenocarcinoma (LUAD) and rectal adenocarcinoma (READ), while the expression of SFTA1P was significantly up-regulated in clear cell kidney carcinoma (KIRC)." (PMID 28977863, 2017). "Interestingly, SFTA1P was later reported to be predominately up-regulated in lung adenocarcinoma and one of the most remarkable enriched functions was surfactant homeostasis by array-based transcriptional survey in 2014." (PMID 28977863, 2017). "In addition, we analyzed the SFTA1P expression level in common LSCC cell lines (NCl-H226, SK-MES-1), lung adenocarcinoma (LUAD) cell lines (NCl-H1299, A549, A549-DDP) and a normal bronchial epithelial cell line (16HBE)." (PMID 29228625, 2017).
lung carcinoma (2 papers, 2020 to 2022). "Previous studies have demonstrated that SFTA1P is downregulated in lung cancers, with such a downregulation associated with cell migration and invasion." (PMID 36344495, 2022). "At present, research on 1ncRNAs in cisplatin resistance in lung cancer was still in its infancy, and some lncRNA molecules related to cisplatin resistance in lung cancer had been screened and identified, including H19, XIST, SFTA1P, CCAT1, and MALAT1." (PMID 32626737, 2020).
non-small cell lung carcinoma (2 papers, 2019 to 2021). A group of at least three distinct histological types of lung cancer, including non-small cell squamous cell carcinoma, adenocarcinoma, and large cell carcinoma. "Functionally, we show that SFTA1P contributes to YAP/TAZ-mediated regulation of non-small cell lung cancer (NSCLC) cell proliferation and survival, therefore conferring tumorigenic properties." (PMID 34845189, 2021).
cervical cancer (1 paper, 2022). A primary or metastatic malignant neoplasm involving the cervix. "In this study, we explore the function and mechanism of lncRNA surfactant associated 1 (SFTA1P) in cervical cancer." (PMID 36344495, 2022). "In conclusion, the lncRNA SFTA1P is up-regulated and associated with poor prognosis in cervical cancer." (PMID 36344495, 2022). "In the present study, we verified that lncRNA SFTA1P is overexpressed in cervical cancer tissues and is associated with poor prognosis." (PMID 36344495, 2022). "Analysis of its mechanism revealed that lncRNA SFTA1P regulates cervical cancer progression by interacting with PTBP1 protein to facilitate TPM4 decay." (PMID 36344495, 2022). "qRT-PCR analysis of 20 pairs of new cervical cancer and adjacent normal tissues also verified that SFTA1P was highly expressed in cervical cancer tissues in most cases." (PMID 36344495, 2022). "The present study revealed that SFTA1P is upregulated in cervical cancer tissues, its higher expression being highly predictive of worse prognosis." (PMID 36344495, 2022). "Kapan-Meier survival analysis based on RNA-seq data of cervical cancer from TCGA showed patients with higher expression of SFTA1P had worse prognosis than those with lower expression of SFTA1P." (PMID 36344495, 2022). "Nude mice in the Sh-SFTA1P (SFTA1P knockdown) group had significantly smaller tumor volume and weight than the control group, suggesting SFTA1P as a promoter of tumorigenicity of cervical cancer cells in vivo." (PMID 36344495, 2022). "To investigate the biological functions of SFTA1P in vitro, we investigated the expression of SFTA1P in seven cervical cancer cell lines." (PMID 36344495, 2022). "Considering that SFTA1P and PTBP1 have the same tumor-promoting roles in cervical cancer, we focused on genes that were simultaneously up- or down-regulated in SFTA1P knockdown and PTBP knockdown cancer cells." (PMID 36344495, 2022). "However, there has been no corresponding studies on SFTA1P in cervical cancer, and any potential roles of SFTA1P in this context remain to be revealed." (PMID 36344495, 2022).
cervical tumor (1 paper, 2022). "SFTA1P is upregulated in cervical tumor tissues and its high expression is associated with poor prognosis." (PMID 36344495, 2022). "According to our previous RNA-seq data, CASP7, EMC6 and PERP were upregulated in cervical tumor tissues, which seemed to conflict with the qPCR results of SFTA1P knockdown." (PMID 36344495, 2022).
colon cancer (1 paper, 2020). "LncRNAs (LINC00402, LINC00461, and SFTA1P) were finally identified as competitive endogenous RNAs (ceRNAs) in association with the occurrence and progression of colon cancer." (PMID 32633726, 2020). "The upregulation of LINC00402, LINC00461, and SFTA1P was verified to enhance the suppressive effects of PHLPP2 in the pathogenesis of colon cancer." (PMID 32633726, 2020). "Conjointly, our results demonstrated the suppressive effects of PHLPP2 in colon cancer and proved that LINC00402, LINC00461, and SFTA1P acted as ceRNAs of PHLPP2 by competitive binding to miR-141 and miR-424." (PMID 32633726, 2020).
lung diseases (1 paper, 2022). "As numerous studies have shown, SFTA1P is closely associated with lung diseases." (PMID 36294833, 2022).
tumor (13 papers, 2018 to 2022). "In summary, our work suggests that the pseudogene-derived lncRNA SFTA1P functions as a tumor suppressor in GC and thus may act as a potential diagnostic and therapeutic target of GC." (PMID 29523596, 2018). "The PFLS consisted of six FElncRNAs, including two risk factors: HOXB-AS3 and SFTA1P, and four protective factors: SLCO4A1-AS1, C1RL-AS1, PCED1B-AS1, and MIR9-3HG, which showed correlations with the HNSCC tumor samples’ overall survival (OS) probability." (PMID 34976018, 2021). "The results showed that the expression of SFTA1P was down-regulated in GC tissues significantly compared with its expression in corresponding non-tumor normal tissues (P-value <0.01)." (PMID 29523596, 2018). "To explore the potential mediators that are involved in the tumor suppressor function of SFTA1P, we tested many genes using qRT-PCR analysis." (PMID 29523596, 2018). "In the prognostic PRlncRNA risk model, 8 lncRNAs (HOTAIR, LINC00402, SFTA1P, LINC00461, DSCR8, CYP1B1-AS1, LINC00330, ALMS1-IT1) were upregulated, while the other 3 lncRNAs (ZRANB2-AS1, MYB-AS1, TP53TG1) were downregulated in tumor tissues." (PMID 35413978, 2022). "HE staining also demonstrated that overexpression of LINC00402, LINC00461, and SFTA1P could enhance the inhibitory effect of PHLPP2 on tumor formation and metastasis." (PMID 32633726, 2020). "Moreover, gain-of-function experiments revealed that the overexpression of SFTA1P inhibits cell proliferation, migration, and invasion, thus verifying the tumor inhibitory role of SFTA1P in GC." (PMID 29523596, 2018). "Taken together, our work shows that SFTA1P could serve as a tumor suppressor and may serve as a marker for GC diagnosis or as a biological target for treating GC." (PMID 29523596, 2018). "After gene differential analysis, we observed that, in tumor samples, CLDN10-AS1 was upregulated, while SFTA1P, SRGAP3-AS2, and ADAMTS9-AS2 were downregulated." (PMID 32149133, 2020). "In tumor tissues, CLDN10-AS1 was upregulated, while SFTA1P, SRGAP3-AS2, and ADAMTS9-AS2 were downregulated." (PMID 32149133, 2020). "The results also confirmed overexpression of LINC00402, LINC00461, SFTA1P, and PHLPP2 or the inhibition of miR-141 and miR-424, could suppress the tumor growth (all p < 0.05)." (PMID 32633726, 2020). "In addition, decreased SFTA1P expression was strongly correlated with advanced tumor lymph node metastasis (TNM) stage, larger tumor size, lymphatic metastasis, and poor prognosis of patients with GC." (PMID 29523596, 2018). "Low expression of SFTA1P showed significant correlations with advanced tumor lymph node metastasis (TNM) stage (P-value =0.002), lymph node metastasis (P-value =0.029), and larger tumor size (P-value =0.026)." (PMID 29523596, 2018). "Moreover, our functional data underscore the value of SFTA1P as a candidate therapeutic target in NSCLC, given that the depletion of SFTA1P resulted in the activation of pro-apoptotic pathways and remarkably compromised tumor growth/induction in vitro and in vivo." (PMID 34845189, 2021).
cancer (7 papers, 2017 to 2025). A tumor composed of atypical neoplastic, often pleomorphic cells that invade other tissues. "SFTA1P expression is correlated with other components of the surfactant machinery, and elevated SFTA1P levels indicate a better prognostic outcome for LUAD cancer patients (cox p-value = 0.009)." (PMID 29113413, 2017). "Interestingly, SFTA1P expression is relatively higher in the NSCLC cell lines compared to non-cancer lines, corroborating its tumorigenic potential in NSCLCs." (PMID 34845189, 2021). "Our results reveal SFTA1P as a positive feedback regulator of Hippo-YAP/TAZ signaling, which may serve as the molecular basis for lncRNA-based therapies against YAP/TAZ-driven cancers." (PMID 34845189, 2021).
SFTA1P also shares sentences with these, for which no sentence is quoted: lung squamous cell carcinoma (3 papers); hepatocellular carcinoma (2); breast carcinoma (1); clear cell kidney carcinoma (1); head and neck cancer (1); head and neck squamous cell carcinoma (1); papillary thyroid cancer (1); rectal adenocarcinoma (1).